GNA11 (G protein subunit alpha 11)
Diseases named in the same sentence as GNA11 in open-access papers (continued):
Sharing a sentence is not in itself a finding about the gene and the disease.
tumor (continued). "Therefore, IHC was employed to further verify the expression of GNA11 at the protein level in ESCC tissues and para-tumor tissues." (PMID 34568004, 2021). "By contrasts, tumor entities that contribute to the second and third main clusters, which is predominated by alterations resulting in GNAQ or GNA11 p.Q209 (indicated by grey bars), mostly show later age at diagnosis and therefore are presumably initiated during adulthood." (PMID 31336681, 2019). "In light of these findings, along with recent studies failing to show a worse prognosis associated with GNA11 mutations, it seems more likely that LOH involving GNAQ and GNA11 is not targeting these genes but rather, one or more tumor suppressor genes on chromosomes 9q and 19p, respectively." (PMID 34400647, 2021). "Since there is no treatment given directly targeting GNAQ/GNA11 mutations, we believe it is less likely that the frequency and pattern of GNAQ/GNA11 mutations changed from the diagnosis of metastasis to the time of tumor specimen procurement in this study." (PMID 34830903, 2021). "We electroporated these DCs either without RNA (mock) or with a panel of 16 different RNAs encoding tumor antigens, or parts thereof (MelanA, NRAS, BRAF, GNAQ, GNA11, and WT1), either mutated or not, and either linked to the lysosomal targeting signal DC-LAMP or not." (PMID 26824052, 2015).
cancer (47 papers, 2013 to 2025). A tumor composed of atypical neoplastic, often pleomorphic cells that invade other tissues. "Together, these results indicated that epigenetic and transcriptional abnormalities in GNA11 were commonly implicated in the tumorigenesis of human cancer." (PMID 37396036, 2023). "Importantly, INPP5A was recently shown to be a highly specific vulnerability in UVM with activating mutations in GNAQ/GNA11, which occur in 90% of these cancers." (PMID 39995872, 2025). "Especially, the presence of co-occurring mutations or epigenetic changes, such as mutations in BAP1, can influence whether a GNAQ or GNA11 mutation leads to a benign lesion or a malignant tumor." (PMID 39518110, 2024). "GNAQ and GNA11 mutations are mutually exclusives and occur in about 2% of human cancers." (PMID 32532044, 2020). "Another alteration caused by GNA11 and GNAQ mutations concerns the calcium signaling pathway, whose dysregulation has a well-documented association with cancer survival, proliferation, migration, and metastatic potential." (PMID 36765733, 2023). "MEK inhibitors have been proven to be effective in cancers with constitutive activation of the MAPK/ERK pathway and have been investigated in UM, which displays GNAQ/GNA11-mutations in >90% of cases." (PMID 34201614, 2021). "Of 87 patients, 21 patients were analyzed by NGS with 48 selected cancer genes including GNA11, GNAQ and FBXW7, and 66 patients were analyzed for mutations by NGS with 592 cancer genes including BAP1 and SF3B1 mutations as well as MYC amplification." (PMID 34830903, 2021). "Of 87 patients, 21 patients were analyzed using TruSeq Amplicom 48 Gene Cancer Panel with the MiSeq system for GNAQ and GNA11 mutations, while the rest were analyzed using 592 genes panel with the NexrSeq instrument for NGS assay." (PMID 34830903, 2021). "For instance, in the current sample, the genes GNAS, GNAQ, and GNA11 were widely altered across cancer types, and these alterations often were accompanied by specific genomic abnormalities in AURKA, CBL, and LYN." (PMID 34150649, 2021). "Cancer genome sequencing efforts have identified frequently mutated genes in UM, including GNAQ, GNA11, BAP1, SF3B1, and EIF1AX7,25." (PMID 32277165, 2020). "Out of the 80 tumors sequenced through the NIH TCGA (The Cancer Genome Atlas) project, 72 had a single mutation in either GNAQ or GNA11 and two tumors had two mutations, one in each gene." (PMID 31173078, 2019). "We hypothesized that, akin to PAK and RAC inhibitors, inhibitors of IMPDH would synergize with inhibitors of MEK in suppressing GNAQ- and GNA11-driven cancer cells." (PMID 41154654, 2025). "GNA11 involves signaling pathways associated with cell survival including PI3K, RAS, and MAPK; and mutations of the corresponding genes could give the cancer cells a selective growth advantage that develop in a restricted nutritional condition." (PMID 34568004, 2021). "The majority of upregulated proteins have been previously linked to tumorigenesis or cancer homeostasis, including signaling molecules (integrin αV, GNAQ, GNA11, the latter two being associated with UM tumorigenesis), molecular chaperon (HSPB1), and an ESCRT-I complex subunit (i.e., TSG101)." (PMID 33050649, 2020). "Thus, there were few co-occurring mutations within the CYSLTR2 mutant cancers (between 5 and 19 coding mutations per sample), intuitively reducing the chance that the enrichment of semaphorin/plexin mutations in CYSLTR2 mutant UM relative to GNAQ/GNA11 mutant UM was a false discovery." (PMID 39013872, 2024).
cancer (continued). "Although biomarkers related to cancer are well studied, autoantibodies to PAX5, PTCH1, and GNA11 were reported in a previous study where their existence and specificity among different ethnic populations were underreported." (PMID 36835134, 2023). "Mutant GNAQ and GNA11 may result in YAP activation and, as a consequence, can lead to cancer formation." (PMID 39518110, 2024). "GNA11 is another gene that was classified as both a TSG and an OG in all three cancer types." (PMID 35620468, 2022). "Moreover, other genes from diverse functional groups appeared in our analysis, such as signal transducers promoting cancer growth (CD53, RAB33A, GNA11, CANX, OCRL, GIPC1, and SOS1), microtubule formation (KIF21B) and cell migration (ASAP2)." (PMID 29535628, 2018). "Interestingly, a new study based on clinical data and next-generation sequencing (NGS) on a cohort of 1348 patients with a wide range of cancers presented the most frequent coalterations in the presence of GNA alterations (GNAS, GNAQ, and GNA11) to be in AURKA, SRC, CBL and LYN genes." (PMID 32532044, 2020). "We show that CD47 is not modulated at different cancer stages, although patients with the lowest expression of CD47 show significant better progression-free survival, after correcting for the presence of BAP1, GNAQ, and GNA11 mutations." (PMID 31277366, 2019).
liver (1 paper, 2021). "All patients had an established UM driver mutation (GNAQ Q209P (35%), GNA11 Q209L (47%), GNAQ R183Q (12%) and CYSTLR2 L129Q (6%)), and metastatic disease involving the liver." (PMID 33917514, 2021).
neurological diseases (1 paper, 2021). "Interestingly, we found that GNAI2 and GNA11 were two mostly shared genes linking profenamine with neurological diseases." (PMID 34131148, 2021).
skeletal dysplasia (1 paper, 2018). Any Mendelian diseases that affects growth and development of the skeleton. "Postnatal molecular genetic analysis found no causative variants in CASR, GNA11, APS21, or a 336 gene skeletal dysplasia panel investigated by whole exome sequencing." (PMID 30144375, 2018).
GNA11 also shares sentences with these, for which no sentence is quoted: autosomal dominant hypocalcemia (5 papers); mucosal (3); cancer of the eye (2); cataract (2); cerebral cavernous malformation (2); colon cancer (2); conjunctival melanoma (2); familial hypercalcemia hypocalciuric types 1 (2); familial melanoma (2); glioma (2); Hypercalciuria (2); Hypocalciuria (2); nevus of Ota (2); ovarian carcinoma (2); Venous malformation (2); acral lentiginous melanoma (1); alcoholism (1); arteriovenous malformations (1); astrocytoma (1); Ataxia (1); atherosclerosis (1); atherosclerotic heart disease (1); atopic dermatitis (1); atrial fibrillation (1); auriculocondylar syndrome (1); autosomal dominant hypoparathyroidism (1); cardiomyopathy (1); chronic hepatitis (1); ciliary body melanomas (1); CNS neoplasms (1).
A further 55 diseases each share a sentence with GNA11 in 1 paper.